EGF (epidermal growth factor)
Diseases named in the same sentence as EGF in open-access papers (continued):
Sharing a sentence is not in itself a finding about the gene and the disease.
tumor (continued). "The other gene sets associated with tumor ranked in top 30 gene sets included hypoxia, tumor environment, NF-kB targets, RHO pathway, EGF response and epithelial differentiation." (PMID 33753999, 2021). "These components are controlled by 10 inputs from the tumour microenvironment (HGF, EGF, ECM stiffness, TGFB, IL6, DELTA, ROS, WNT and the ligands for RPTP and FAT4)." (PMID 34063110, 2021). "It is known that CARMA3 functions as a modulator in downstream NF-κB activation in response to receptor activation, such as epidermal growth factor (EGF) receptor and angiotensin II receptor, inducing tumor growth and progression." (PMID 34885061, 2021). "Tumor cells secrete growth factors such as VEGF, EGF, FGF, interleukins, and IFN, which stimulate surrounding cells in the tumor tissues to release MMPs, allowing tumor cells to migrate." (PMID 35145899, 2021). "Moreover, EGF in the tumor microenvironment may also influence the behavior of cancer cells." (PMID 34572344, 2021). "Various signals, including EGF, can stimulate PKM2 acetylation at K433, which is required for nuclear function and contributes to the tumor progression." (PMID 34439090, 2021). "For instance, epidermal growth factor (EGF) withdrawal allows for the selection of rat sarcoma viral oncogene homologue (RAS) mutants, hence EGF receptor (EGFR)–signalling independent tumour cells." (PMID 33057820, 2021). "Well-established signals that promote EMT in various tumor cell models are induced by TGF-β and growth factors including FGF, EGF and HGF." (PMID 33481051, 2021). "Increase of Bax/Bcl-2 ratio and decrease of Ki67 protein expression; decrease of blood concentrations of tumor growth factors and tumor concentrations of VEGF and EGF expressions." (PMID 34630112, 2021). "In support of this notion, pharmacological or genomic approaches targeting ATF6 induced a significant decrease in EGF transcription and angiogenesis-stimulating activities in SCCs, effectively suppressing the SCC-derived tumor growth." (PMID 32630838, 2020). "The mitogens, known as tumor promotors, EGF (epidermal growth factor) and TPA (12-O-tetradecanoylphorbol-13-acetate) stimulate the degradation of PDCD4 protein." (PMID 31952347, 2020). "In this study, we performed in vitro cell experiments to confirm that piperlongumine did have an anti-tumor effect on HCC, which was achieved through the inhibition of EGF/EGFR signaling pathway-induced angiogenesis." (PMID 32379058, 2020). "ADAM-12 exhibits catalytic activity by cleaving certain ligands that are biologically important for tumour growth, such as tumour necrosis factor-alpha (TNF-α), epidermal growth factor (EGF), and transforming growth factor-alpha (TGF-α)." (PMID 32386517, 2020). "The oncogenes Kristen rat sarcoma 2 viral oncogene homolog (KRAS), epidermal growth factor (EGF) and SRC are transferred by exosomes to recipient tumor cells to promote tumor invasion." (PMID 33396739, 2020). "The mechanism underlying angiogenesis is mostly modulated by chemical stimuli such as vascular endothelial growth factor (VEGF), fibroblast growth factor (FGF), angiopoietins, epidermal growth factor (EGF), etc., all of which are plentiful at tumor sites." (PMID 33195249, 2020). "Among others, these tumor and stroma-derived growth factors and cytokines include interleukines (IL), chemokines (CXC), tumor necrosis factor-alpha (TNF), epidermal growth factor (EGF), vascular endothelial growth factor, and fibroblast growth factor (FGF)." (PMID 32660072, 2020). "This is postulated to happen through tumor microenvironment mediators such as TNF-α, vascular endothelial growth factor and epidermal growth factor." (PMID 33344090, 2020). "According to experimental evidence, EGF has been known to improve cell motility and invasiveness by MMP-2 activation, results in cancer cells enable cross several ECM barriers during tumor metastasis." (PMID 32376896, 2020).
tumor (continued). "The EMT is a common process, in which a group of transcription factors and the tumor microenvironment (TME) are involved through diverse signals, such as Snail, Slug, ZEB1, Twist, TGF-β, EGF, Wnt, and Notch34." (PMID 32587771, 2020). "On this note, the tumor microenvironment secretes cytokines (e.g., SDF-1, EGF, PDGF, TNF-α and IL-8) that recruit MSCs into the tumor mass." (PMID 33143238, 2020). "Different types of cell factors, such as vascular endothelial growth factor (VEGF), epidermal growth factor (EGF), and interleukin-1β (IL-1β), are released during platelet activation and promote tumor growth and angiogenesis." (PMID 31768743, 2020). "The formation of new vessels, also known as angiogenesis, supports tumor growth and it is tightly regulated by angiogenic activators including VEGF, FGF, PDGF, and EGF." (PMID 32257947, 2020). "IL-31 can also significantly upregulate the gene expression and protein levels of epidermal growth factor (EGF) and VEGF, both involved in angiogenesis, tumor growth, and metastasization." (PMID 32069819, 2020). "The Abl family of non-receptor tyrosine kinase (Arg) also mediates epidermal growth factor (EGF)-induced cortactin phosphorylation, triggering actin polymerization in invadopodia, ECM degradation, and tumor cell invasion." (PMID 32104508, 2020). "In brief, macrophages secrete epidermal growth factor (EGF), which interacts with its target receptor (EGFR) on the surfaces of tumor cells." (PMID 32182935, 2020). "Next, to dissect the mechanism of how ERβ can increase the HUVEC tube formation, we focused on tumor angiogenesis-related genes, including Angiogenin, ANGPT-2, bFGF, EGF, HB-EGF, HGF, Leptin, PLGF, and VEGF-A35." (PMID 32409702, 2020). "Platelets release growth factors such as PDGF, EGF and VEGF to induce tumor angiogenesis and increase the permeability of blood vessels by releasing MMPs, 5-hydroxytryptamine and histamine." (PMID 31980023, 2020). "Here, heterotypic TNTs were seen to enhance the invasive phenotype of tumor cells in an EGF-EGFR-dependent manner and to be critical to the directional streaming of tumor cells toward the endothelium." (PMID 33521055, 2020). "Activation of the JAK2/STAT3 pathway in CAFs provokes the release of epidermal growth factor, EGF, which promotes the EMT in tumor cells." (PMID 33363032, 2020). "In the tumor microenvironment, M2 macrophages play critical roles in the process of angiogenesis through the secretion of VEGFA, epidermal growth factor, and interleukin-8." (PMID 32075061, 2020). "Immunofluorescence imaging showed that treatment with EGF-PLGA@5Fu/PFC NPs treatment significantly weakened pimonidazole green fluorescence compared with that in the control group, which indicated decreased tumor hypoxia." (PMID 32345258, 2020). "Most of these angiogenic factors are molecular components of the EGF/PDGF pathway, which plays an important role in activating tumor angiogenesis." (PMID 33330033, 2020). "In a mouse model of PCa, ADAM9 was shown to play a critical role in tumor progression which was attributed to the ability of ADAM9 to cleave and release EGF and FGFR2 from cells." (PMID 32719332, 2020). "Pharmacological analysis of the inhibitor of EGF/EGFR, piperlongumine, had been shown to have an anti-tumor effect on HCC, which was achieved through inhibiting angiogenesis via the EGF/EGFR signaling pathway." (PMID 32379058, 2020). "In vitro cell studies verify specific binding of EGF-decorated lipodisks to tumor cells and confirm that targeted delivery of VIP116 significantly decreases tumor cell viability." (PMID 32325827, 2020). "This suggested role may provide a molecular mechanism by which TSG101 could act as a tumor suppressor, and it was reported that ‘TSG101-deficient’ SL6 cells exhibited alterations in EGF trafficking that may have caused elevated levels of active MAP kinases following EGF stimulation." (PMID 32075127, 2020).
tumor (continued). "It has been reported that coactivation of EGF and EGFR drives tumor metastasis via PI3K/AKT-dependent pathways." (PMID 32045997, 2020). "Essentially, CAFs can promote angiogenesis and tumor growth by producing VEGF, TGF-β, fibroblast growth factor (FGF), platelet-derived growth factor (PDGF), and epidermal growth factor (EGF)." (PMID 33117708, 2020). "Annexin 8 (ANXA8), which is also down-regulated, has been shown to be transcriptionally down-regulated by epidermal growth factor (EGF), which correlates with the morphologic changes of EMT, along with tumour dedifferentiation." (PMID 33225905, 2020). "In vivo, tumor volume and weight were reduced, and the expression of VEGF, EGF, IL-10, TGF-β, and CD34 was suppressed in the tumor microenvironment, while cell apoptosis was induced." (PMID 32595723, 2020). "Recently, numerous growth factors (EGF, TGF-β) and cytokines (e.g., IL-6) have been reported to support tumor growth and spreading." (PMID 32443749, 2020). "Inherbin3, an antagonist of epidermal growth factor (EGF)-EGFR signaling, inhibits EGF-induced EGFR phosphorylation, cell growth and migration in human tumor cell lines and suppresses tumor growth in a tumor xenograft model." (PMID 32001707, 2020). "Within the TME, M2-like TAMs promote cancer cell proliferation through the activation of the MMP9/HB-EGF pathway and epidermal growth factor (EGF) production, leading to the stimulation of VEGF signaling that supports tumor metastasis." (PMID 32354198, 2020). "Despite the quality of our first version of EGF/rGel which suffered from impurities and significantly reduced gelonin activity as compared to unmodified gelonin, EGF/rGel-PCI was shown highly tumor specific and potent in two xenograft models." (PMID 32075165, 2020). "Macropinocytosis normally occurs in response to stimulation by growth factors such as the macrophage colony-stimulating factor-1 (CSF-1), the epidermal growth factor (EGF) and the platelet-derived growth factor or tumor-promoting factors." (PMID 31976201, 2020). "This study showed that WAVE3 phosphorylation supports tumor growth in BC and does so at least in part through its activation downstream of PI3K/TGF-β/EGF oncogenic signaling pathways." (PMID 33012785, 2020). "It is noteworthy that activation of the MAPK/ERK and PI3K/Akt pathways is an important step required for EMT process induced by various tumor-related factors including TGF-β, TACC3, EGF, BMP7, ZNF143, and CXCR4 26-31." (PMID 31417642, 2019). "MEIS1 silencing resulted in suppression of the involved genes in cell proliferation (EGF) and EMT (TWIST1), leading to tumor cell differentiation in ESC cell line KYSE‐30." (PMID 31090196, 2019). "Epiregulin (EREG), which is mainly secreted by fibroblasts, is a member of the epidermal growth factor (EGF) family of peptide growth factors and promotes tumor development, migration and invasion." (PMID 31234944, 2019). "Previous studies revealed that EGF activated EGFR and led to the activation of downstream signaling pathways, such as PI3K/AKT and MAPK/ERK, which are critical in metastasis and tumor progression." (PMID 31171012, 2019). "In contrast, inhibition of EGF signaling decreases VEGF-A production and thus inhibits angiogenesis and tumor growth." (PMID 31717527, 2019). "On the other hand, TAMs hijack tumor cells into the circulation by a positive feedback loop consisting of tumor cell-produced CSF-1 and TAM-produced EGF." (PMID 31300030, 2019). "For example, tumor-resident macrophages (M2 polarized macrophages) secret vascular endothelial growth factor (VEGF) and epidermal growth factor (EGF), which induce angiogenesis and the recruitment of neutrophils contribute to tumor progression and metastasis." (PMID 31861498, 2019). "To further ascertain the role of EGF/EGFR signaling in OC peritoneal dissemination, we used CRISPR/Cas9 editing to knock down EGFR in OC tumor cells." (PMID 30710055, 2019).
tumor (continued). "Specifically, a positive correlation between urine GOAT levels and the expression levels (in the tumor pieces) of CDK6, EGF, EZH2 and NF-KB was found in patients with PCa." (PMID 31766715, 2019). "We found that subcutaneous injection of as few as 5 × 102 A549 cells with ectopic EGF expression led to growth of tumors, whereas at least 5 × 104 control NSCLC cells were required to form a tumor." (PMID 30177836, 2019). "In parallel, a recent study demonstrated that inhibition of the EGF/EGFR signaling axis reduced spheroid formation between ATCs and macrophages, and eventually attenuated OC tumor growth in a mouse model." (PMID 30710055, 2019). "EGF, b-fibroblast growth factors (b-FGF) and insulin are the three major components in our sphere-formation pelletizing system, which also exist in the tumor microenvironment." (PMID 31501409, 2019). "In multiple tumor cell lines, SAP has been shown to be a much more potent inhibitor of EGF-driven cellular proliferation than gefitinib." (PMID 35529145, 2019). "Poly-SUMOylated OTUB2, which was induced by Epidermal growth factor (EGF) and oncogenic KRAS, was shown to bind and activate YAP/TAZ promoting tumor metastasis." (PMID 31619007, 2019). "We found a 1.6-fold increase in the growth rate of primary FL-HCC tumor slices after JMV treatment compared to controls, further supporting the co-mitogen effect of NTS with EGF." (PMID 31489118, 2019). "The tumor-promoting activities of TAMs depended on direct interaction with EOC cells and local production of EGF." (PMID 31817625, 2019). "TAM cells secrete epidermal growth factor (EGF) and TNF-α, while tumor cells secrete colony-stimulating factor-1 (CSF-1)." (PMID 31192126, 2019). "Peripheral microglia are attracted and recruited inside the tumor core by the secreted factors released from the tumor cells like CCL2, CSF1, or EGF." (PMID 31824268, 2019). "When the EGF level is below the threshold value GF0*, the tumor cells will either die by apoptosis or will keep switching back and forth between the dormant and proliferating state until they die." (PMID 31157216, 2019). "Other signals that regulate the EMT and originate from the tumor include growth factors including HGF, EGF, and PDGF and these are thought to activate EMT-related transcription factors." (PMID 31467533, 2019). "The relationship between epidermal growth factor (EGF) and vascular endothelial growth factor (VEGF) pathways in tumor growth is well established." (PMID 31717527, 2019). "TAMs secrete large amounts of EGF to activate the EGF receptor (EGFR) in surrounding tumor cells, thereby supporting tumor proliferation and anoikis protection." (PMID 31096567, 2019). "The upregulation of ELTD1 ([epidermal growth factor (EGF), latrophilin and seven transmembrane domain-containing 1] on chromosome 1) in tumor cells has been reported in several types of cancer and correlates with poor cancer prognosis." (PMID 31554859, 2019). "There are only few studies that tested serum levels of PlGF and EGF in patients with CRC indicating PlGF and EGF as potential prognostic markers of tumor recurrence and survival." (PMID 31358848, 2019). "Tumor cell isolates were cultured under serum-free conditions for generally 2 to 4 weeks with epidermal growth factor (EGF) and basic fibroblast growth factor (FGF) supplements for enrichment of tumor initiating cell (TIC) populations." (PMID 31771620, 2019). "Following delivery into the tumour, liposomes are internalised into EGFR-overexpressing cells via the EGF present on their surface ensuring co-delivery of Dox and 111In." (PMID 31534505, 2019). "This is evident by the secretion of factors involved in extracellular matrix degradation like MMPs or in angiogenesis like VEGF, EGF, or IL1B, which are needed for tumor growth and the invasion into the healthy tissue." (PMID 31824268, 2019).
tumor (continued). "Wycoff and colleagues demonstrated how TAMs, usually located at the edge of the tumours, are stimulated by colony stimulating factor 1 (CSF1) to produce epidermal growth factor (EGF), the EGFR natural ligand." (PMID 31554160, 2019). "EMT can be induced by various signaling pathways (TGF-β, Wnt/β-catenin, Notch, FGF, EGF, and HGF) and hypoxia in tumor progression." (PMID 31399111, 2019). "In the majority of cases, tumor development is dependent on signaling via the epidermal growth factor receptor (EGFR) and requires EGF in lower-grade forms or is EGF-independent in the more aggressive forms." (PMID 31386654, 2019). "Mechanistically, we demonstrated that tumor cells promote EGF secretion by CAFs within the MU microenvironment that consequently drives ITGA5 expression in ATCs, which in turn further strengthens the tumor–stromal interaction inside MUs." (PMID 30710055, 2019). "Several signaling pathways, including TGF-β, Wnt/β-catenin, Notch, FGF (Fibroblast growth factor), EGF (Epidermal growth factor), and HGF (Hepatocyte growth factor), as well as hypoxia can induce EMT in tumor progression." (PMID 31399111, 2019). "EGF induces VEGF production in cancer cells, and the paracrine VEGF activates vascular endothelial cells to promote tumor angiogenesis and thus supports tumor cell growth in an angiogenesis-dependent manner." (PMID 31717527, 2019). "Tumor angiogenesis is initiated among others by growth factors secreted by tumor cells into the hypoxic tumor microenvironment such as VEGF, EGF and many others." (PMID 29772843, 2018). "In this study, we showed that the knockdown of G3BP1 dramatically impaired EGF-induced RCC cell chemotaxis, an essential component of tumor dissemination during progression and metastasis, indicating EGF-mediated chemotaxis in RCC is probably via G3BP1." (PMID 29717134, 2018). "EGFR subjected to low concentrations (< 2 ng/ml) of EGF are internalized via CME and this is the physiologically relevant concentration in tumours." (PMID 30409180, 2018). "It was documented that EGF and its receptor EGFR are frequently overexpressed in many forms of RCC, and signaling cascade through EGF/EGFR/STAT3 play an important role in tumor cell growth and EMT in RCC33,35,46." (PMID 29717134, 2018). "In contrast to VEGF and EGF, PD1/PD-L1, as well as CTLA-4 are immune checkpoints that negatively regulate T-cell immune functions, thus indirectly promoting tumor progression via tumor immune escape." (PMID 30577587, 2018). "Tumor and endothelial cells were seeded, respectively, in these two channels to mimic tumor cell invasion through 3-D ECM, in response to externally applied growth factor, such as epidermal growth factor (EGF), or biochemical gradients." (PMID 29561794, 2018). "Cues from the tumor microenvironment, such as transforming growth factor (TGF) β and epidermal growth factor (EGF), promote EMT initiation and represent potential targets to disrupt the process." (PMID 30366428, 2018). "In the case of TNBC, cancer metastasis involves tumor microenvironment factors as peripheral signals including epidermal growth factor (EGF) and insulin-like growth factor I (IGF-I) at distant tumor sites." (PMID 29881724, 2018). "For tumor sphere formation, we seeded MCF-7 cells in DMEM/F12 media containing the growth supplements EGF, bFGF, and B27 in low-attachment six-well plates." (PMID 29914089, 2018). "Chemotaxis-based experiments and intravital imaging revealed that reciprocal signaling between tumor cell-derived CSF-1 and TAM-derived EGF is essential for the promotion of tumor cell migration." (PMID 30356678, 2018). "Induction of EGF ligands (BTC, EGF, and EREG) was similarly observed in fibroblasts from adjacent normal tissue (>10 cm from tumor) in a second patient." (PMID 30018330, 2018). "This paracrine loop involving EGF and CSF1 is crucial for tumor invasion, and the inhibition of either signaling pathway inhibits the migration of both cell types." (PMID 29594035, 2018).